MEA1 (male-enhanced antigen 1)
Description:
May play an important role in spermatogenesis and/or testis development.
Synonyms: MEA; HYS
Tractability: PROTAC: ubiquitination databases record sites on it.
Gene: Protein-coding gene on chromosome 6 (43,011,143 to 43,016,868, reverse strand). Ensembl gene ENSG00000124733.
Subcellular location (Human Protein Atlas): Cytosol; Nucleoplasm
Gene Ontology:
Molecular function: protein binding
Biological process: male gonad development; spermatogenesis
Cellular component: cytoplasm
Genetic constraint (gnomAD): Loss-of-function variants: 22 observed, 21.85 expected, observed/expected ratio (o/e) 1.01, 90% interval 0.72 to 1.44. The upper end of that interval is the gene's LOEUF score, 1.44, which puts it in group 5 of 6, group 1 being the genes least tolerant of losing a copy. Missense variants: 233 observed, 241.17 expected, observed/expected ratio (o/e) 0.97, 90% interval 0.87 to 1.08. Synonymous variants: 91 observed, 90.64 expected, observed/expected ratio (o/e) 1, 90% interval 0.85 to 1.2.
Homologues: Orthologues: chimpanzee MEA1 (100% identical), macaque MEA1 (96% identical), dog MEA1 (92% identical), rat Mea1 (92% identical), pig MEA1 (91% identical), rabbit MEA1 (91% identical), mouse Mea1 (88% identical), guinea pig MEA1 (86% identical), tropical clawed frog mea1 (51% identical), zebrafish mea1 (45% identical), Drosophila melanogaster CG14341 (18% identical).
Diseases named in the same sentence as MEA1 in open-access papers:
MEA1 is named in the same sentence as 10 diseases in open-access papers, as found by Europe PMC text mining. Sharing a sentence is not in itself a finding about the gene and the disease. The quoted sentences say what the papers report.
basal cell carcinoma (1 paper, 2025). A carcinoma involving the basal cells. "Our studies found that MEA1 negatively correlated with the abundance of most immune cells upregulated in tumor tissue and the results of various pathways, including gastric cancer, breast cancer, basal cell carcinoma, and downregulated translation repressor activity." (PMID 40725242, 2025).
MEA1 also shares sentences with these, for which no sentence is quoted: Anxiety (3 papers); asthenospermia (1); breast carcinoma (1); cancer (1); depression (1); gastric cancer (1); generalized anxiety disorder (1); oligospermia (1); tumor (1).